OTX2 (orthodenticle homeobox 2)
Diseases named in the same sentence as OTX2 in open-access papers (continued):
Sharing a sentence is not in itself a finding about the gene and the disease.
microphthalmia (continued). "The major phenotype reported in patients with OTX2 mutations consists of isolated or syndromic microphthalmia/anophthalmia, possibly associated with extra-ocular defects such as brain malformations, pituitary abnormalities, short stature and intellectual disability." (PMID 30268123, 2018). "Moreover the study showed that OTX2 loss-of-function mutations are associated with a broad spectrum of ocular phenotypes, ranging from bilateral anophthalmia to mild microphthalmia with retinal abnormalities." (PMID 24250932, 2013). "Notably, OTX2 mutations are linked to the etiology of 2–3% of anophthalmia/microphthalmia cases." (PMID 37181651, 2023). "Mutations in OTX2, RAX and CHX10, three genes expressed in the retina, are reportedly associated with anophthalmia/microphthalmia, possibly causing failure of retinal differentiation." (PMID 40038803, 2025). "Gene knockdown studies have already identified that the endogenous functions of pax6a, pax6b, vsx1, otx2, and rx1 are clearly involved in the eye morphogenesis of vertebrates, and changes in the expression levels of these genes could cause various eye diseases, like microphthalmia." (PMID 38251014, 2024). "Previous research has linked mutations in genes such as CHX10, MAF, PAX6, PAX2, RX (RAX), SHH, SIX3, OTX2, and SOX2 to phenotypes associated with microphthalmia, anophthalmia, and coloboma (MAC)." (PMID 39129019, 2024). "From these 9 patients with intolerant OTX2 variants, 6/9 had developmental delay, 6/9 had IGHD, and 7/9 had an eye phenotype ranging from retinal dystrophy or ONH to the more severe microphthalmia." (PMID 33950863, 2021). "Depending on the genetic background, Otx2+/− embryos show variable phenotype (acephaly, holoprosencephaly, short nose, anophthalmia/microphthalmia, agnathia/micrognathia, or normal phenotype)." (PMID 32111086, 2020). "Mosaicism has been confirmed in other OTX2 cases, such as a patient with bilateral severe microphthalmia who was the daughter of a phenotypically normal mother shown to have low levels of the variant in blood and buccal DNA, indicating gonosomal mosaicism." (PMID 31416264, 2019). "Homozygous mouse knockouts of homeobox gene Otx2 lack eyes, while heterozygous knockout mouse models also show a highly variable phenotype, from acephaly, micrognathia, anophthalmia, microphthalmia to normal development, depending on the genetic background." (PMID 31416264, 2019). "As microphthalmia is very rarely reported in aniridia, and in some cases is thought to be caused by mutations in other important eye genes such as SOX2 and OTX2 in addition to the aniridia causing PAX6 mutation." (PMID 30258099, 2018). "Otx2+/− mice can be normal, have developmental eye anomalies including anterior segment malformations, severe eye abnormalities such as microphthalmia or anophthalmia, or head abnormalities." (PMID 19956411, 2009). "Further sequence analysis of other genes associated with anophthalmia and microphthalmia such as PAX6, BCOR, OTX2, SIX6, and CHD7 is ongoing in this study cohort to determine mutation associations." (PMID 18385794, 2008). "Additionally, previous studies showed that mutations in human OTX2 and RAX lead to anophthalmia, microphthalmia, and coloboma, findings that are in line with the eye phenotype upon bop1 knockdown in our study." (PMID 36007075, 2022). "The OTX2 gene is associated with syndromic diseases, such as microphthalmia and retinal degeneration with or without pituitary dysfunction (OMIM: 610125; 610125)." (PMID 34327195, 2021). "Otx1 and Otx2 mutant mice showed no retinal pigmented epithelium development, while Otx2 mutations are associated with several eye defects such as microphthalmia or the lack of a lens, cornea, and iris." (PMID 35003791, 2021).
microphthalmia (continued). "Mutations occurring in the orthodenticle homeobox 2 gene (OTX2) are responsible for a rare genetic syndrome, characterized mainly by microphthalmia/anophthalmia associated with extra-ocular defects such as brain malformations, pituitary abnormalities, short stature and intellectual disability." (PMID 30268123, 2018). "Similar to what has been observed in zebrafish, mutations in OTX2 but not MITF have been identified in cases of severe human RPE developmental abnormalities such as microphthalmia and anophthalmia." (PMID 23139843, 2012). "However, mutations in VSX2, CRYBA4, OTX2, and RAX have been detected in about 2%–3% patients with microphthalmia, anophthalmia, and coloboma." (PMID 20057906, 2009). "Interestingly, inflammation/TNF‐α‐dependent OTX2 downregulation might also have implications in congenital microphthalmia and auditory defects, common after intrauterine infections, notably with cytomegalovirus (CMV)." (PMID 27660103, 2017). "Similarly, incomplete penetrance and variable expressivity have been observed in families with heterozygous mutations in orthodenticle homeobox 2 (OTX2) or bone morphogenetic protein 4 (BMP4), which are associated with anophthalmia/microphthalmia or severe anterior segment dysgenesis." (PMID 22815627, 2012). "Seventy patients having non-syndromic forms of colobomatous microphthalmia (n=25), isolated microphthalmia (n=18), or anophthalmia (n=17), and syndromic forms of micro/anophthalmia (n=10) were included in this study after negative molecular screening for OTX2, RAX, SOX2, and CHX10 mutations." (PMID 21203406, 2010). "Mutations in several genes have been reported in patients with microphthalmia and/or coloboma, including BMP4 (OMIM 112262), VSX2 (CHX10; OMIM 142993), CRYBA4 (OMIM 123631), OTX2 (OMIM 600037), RAX (OMIM 601881), SIX6 (OMIM 606326), and SOX2 (OMIM 184429)." (PMID 20057906, 2009). "OTX2, CHX10 and RAX have retinal expression and may result in anophthalmia/microphthalmia through failure of retinal differentiation." (PMID 18039390, 2007). "Disruption of the Otx2 transcription factor binding site in one of these elements (CE14) in Xenopus tropicalis reduced expression of mab21l2 in neurula stage embryos and resulted in microphthalmia, lens defects and coloboma, confirming its importance in eye development." (PMID 39455595, 2024). "Other family members have serious yet isolated features: a cardiac malformation (II.2), an ear malformation (III.3) and microphthalmia (III.5) without GHD, possibly highlighting the highly variable phenotypes stemming from haploinsufficient OTX2." (PMID 33950863, 2021).
Anophthalmia (32 papers, 2007 to 2025). Absence of the globe or eyeball. "Mutations in OTX2 lead to a spectrum of ocular malformations, including anophthalmia, microphthalmia, coloboma, and retinal dystrophies, sometimes accompanied by hypopituitarism." (PMID 41303332, 2025). "Clinically, this provides a developmental correlate to the phenotypic variability of human OTX2 mutations, which range from bilateral anophthalmia to retinal dystrophies." (PMID 41303332, 2025). "An OTX2 mutation is associated with anterior pituitary hypoplasia and ectopic posterior pituitary along with severe ocular malformation, including anophthalmia." (PMID 40539145, 2025). "Phenotypic outcomes, even within the same family, of OTX2 mutations range from subclinical to micro/anophthalmia but also include otocephaly and dysgnathia." (PMID 30073412, 2019). "In our cohort, a mutation in the OTX2 gene was identified as the molecular cause of bilateral anophthalmia (pedigree MA_1)." (PMID 29178648, 2017). "A novel heterozygous OTX2 missense mutation was identified in a patient showing bilateral anophthalmia who inherited the variant from a parent who was a carrier, but showed no sign of the condition." (PMID 29178648, 2017). "A screen for heterozygous loss-of-function mutations in either SOX2 or OTX2 should clearly be the first line test that will have a significant detection rate in cases of anophthalmia." (PMID 24498598, 2013). "A further case of anophthalmia associated with an OTX2 mutation was reported to have isolated growth hormone deficiency and short stature." (PMID 19956411, 2009). "A similarly remarkable example is family F141 where an OTX2-related inherited retinal degeneration with female infertility caused by a homozygous cryptic splicing variant is a stark contrast to the dominant OTX2-related anophthalmia phenotype." (PMID 37644014, 2023). "Key genetic contributors to bilateral anophthalmia include de novo, heterozygous, loss-of-function mutations in SOX2 or OTX2, which regulate crucial eye development pathways such as optic vesicle formation and forebrain specification." (PMID 40843047, 2025). "Indirectly, SHH may also mediate the local effects of OTX2 mutations on both eye and jaw in human micro/anophthalmia with or without otocephaly and micro/agnathia." (PMID 30073412, 2019). "Inactivation of Wnt signalling activator β-catenin in mice at the optic vesicle stage results in a lack of Otx2 and Mitf signalling in the optic cup, and expansion of the NR domain, leading to anophthalmia." (PMID 31416264, 2019).
retinoblastoma (15 papers, 2014 to 2024). A malignant tumor that originates in the nuclear layer of the retina. "In a retinoblastoma study, loss of OTX‐2 expression also causes a decrease in C‐MYC expression, one of the genes involved in retinoblastoma tumorigenesis." (PMID 38925618, 2024). "Loss of OTX2 expression may play a role in retinoblastoma development by contributing to the increase in phosphorylation of RB and its effects." (PMID 36012688, 2022). "A platform for initiation of retinoblastoma in a developing human retina in vitro would allow unique freedom to test various temporal settings for the mutagenic events e.g. loss of RB1 function on different levels or gain of a MYCN or OTX2 amplification at different steps in retinal development." (PMID 29124525, 2017). "In another study, OTX‐2 overexpression was detected in 86% (19/22) of the main adult retinoblastoma tumors examined." (PMID 38925618, 2024). "Overexpressing OTX2 increased irbp promoter-luciferase activity by 5–7-fold in WERI-Rb1 retinoblastoma cells, suggesting that OTX2 activates the irbp promoter." (PMID 33328889, 2020). "In our collection of retinoblastomas, MDM4 and OTX2 copy number gains were found in 16 (42%) and five (13%) of 38 retinoblastoma, respectively." (PMID 28211617, 2017). "Other copy number changes reported in retinoblastoma include gains of DDX1, MDM4 and OTX2, and loss of BCOR and RBL2." (PMID 29124525, 2017). "Aberrant overexpression of OTX2 has been detected in both retinoblastoma tumors and cell lines, which makes it plausible that there is a link between the photoreceptor-like characteristics in these cancer cells and the proposed cell-of-origin." (PMID 29124525, 2017). "Pharmacologic inhibition of OTX2 via all-trans retinoic acid (ATRA) caused increased apoptosis, decreased proliferation and colony formation in retinoblastoma cell lines." (PMID 29124525, 2017). "Retinoblastomas express a variety of rod and cone photoreceptor genes and it will be important to determine if OTX2 plays a role in modulating the photoreceptor differentiation program in retinoblastoma in future studies." (PMID 24509483, 2014). "Taken together, our data suggest that MYCN and OTX2 are the most common focal gains found in retinoblastoma and RB1, and BCOR are the most common focal losses found in retinoblastoma." (PMID 24509483, 2014). "Group 3 MB and retinoblastoma, along with the normal cerebellum and retina —both of which are known to express high levels of OTX2—exhibited unique PPHLN1 and MADD splicing patterns." (PMID 39025928, 2024). "Levels of pRB in retinoblastoma were shown to be elevated by OTX‐2 inhibition." (PMID 38925618, 2024). "Only the lymph node metastasis and HPG-RBG1 cells showed a high-level amplification (>20×) in 14q harboring OTX2 (a gene that has been described as amplified in retinoblastoma), as well as other focal gains or amplifications in 2q, 11q and 14q that did not include cancer-related genes." (PMID 32971811, 2020). "In addition to the previously reported recurrent focal losses of RB1 and BCOR and amplification of MYCN, we also identified a recurrent focal amplification of OTX2 in 3% of retinoblastomas." (PMID 24509483, 2014). "We also identified focal amplification in OTX2 in 3% (3/94) retinoblastoma samples." (PMID 24509483, 2014). "Here we identified a new recurrent focal amplification of OTX2 in 3% of retinoblastomas." (PMID 24509483, 2014). "Focal amplifications of the orthodenticle homeobox 2 gene (OTX2) were observed in 3% and focal deletions of the BCL6 Corepressor (BCOR) observed in 4% of the same cohort of retinoblastoma tumours." (PMID 33670346, 2021). "Examining retinal proteins in retinoblastoma has shown that transcription factors cone-rod homeobox protein (CRX) and homeobox protein OTX2, which specify fate decision for photoreceptors, are widely expressed in retinoblastoma." (PMID 32824373, 2020).
retinoblastoma (continued). "The high expression of OTX2 and CRX in RB tumors and cell lines suggested that retinoblastomas may originate from cells normally expressing these transcription factors, such as bipolar cells or photoreceptor precursors." (PMID 38069286, 2023).
hypopituitarism (12 papers, 2009 to 2025). A condition of diminution or cessation of secretion of one or more hormones from the anterior pituitary gland. "Given that the growth of the pituitary stem and hind lobe depends on OTX2, it follows that OTX2 mutations cause hypopituitarism in both humans and mice." (PMID 39812047, 2025). "All of the patients we report with OTX2 mutations in our large multi-ethnic cohort had hypopituitarism and variable eye abnormalities." (PMID 33950863, 2021). "The frequencies of eye abnormalities and pituitary insufficiency in patients with OTX2 variants are 78 and 30%, respectively." (PMID 33950863, 2021). "This phenotype differs from the severe eye defects that usually accompany hypopituitarism in the majority of patients with OTX2 mutations." (PMID 33950863, 2021). "As OTX2 is essential in retinal development, many patients with OTX2 mutations and pituitary hormone deficiencies also present with a variety of ocular abnormalities." (PMID 33634051, 2020). "It is noteworthy that 2 of these LCA cases (RP-1613 and RP-2140), had diverse symptoms of hypopituitarism, and both bore de novo nonsense OTX2 variants: p.(Trp85*) and p.(Gln187*), respectively." (PMID 29588463, 2018). "Recently, the role of OTX2 in pituitary development has been further delineated with three case reports of OTX2 mutations associated with pituitary hormone deficiency (CPHD)." (PMID 19956411, 2009). "This study provides evidence of a novel mutation in OTX2 associated with early onset retinal dystrophy and pituitary insufficiency." (PMID 19956411, 2009). "In conclusion, extra-pituitary findings may provide clues for the diagnosis of particular gene mutations including GLI2, HESX1, LHX4, SOX3, and OTX2 which are involved in the development and differentiation of the pituitary gland resulting in a variety of pituitary hormone deficiencies." (PMID 31782289, 2020). "Heterozygous mutations of orthodenticle homeobox 2 (OTX2)can result in ocular malformations, pituitary abnormalities, or hypopituitarism spanning from isolated growth hormone (GH) deficiency to combined pituitary hormone deficiency." (PMID 38249203, 2023). "We sought to establish the frequency of OTX2 variants in our large multi-ethnic cohort of patients with hypopituitarism in the presence and absence of eye abnormalities and to study their functional consequence." (PMID 33950863, 2021). "This is the first OTX2 frameshift/early stop codon mutation, as opposed to two previous OTX2 missense variants, reported in a patient with hypopituitarism in isolation." (PMID 33950863, 2021). "We describe the third case to date, of a patient with an OTX2 mutation with congenital hypopituitarism without eye abnormalities (patient 9)." (PMID 33950863, 2021). "OTX2 hemizygous deletions and non-synonymous point mutations have been reported in patients with severe ocular malformations, developmental delays, and hypopituitarism, symptoms that are not seen in our pedigree." (PMID 24816892, 2014). "Hypopituitarism can have a congenital cause due to mutations in genes involved in pituitary development and endocrine cell differentiation, such as POU class 1 homeobox 1 (POU1F1, also known as PIT1) and orthodenticle homeobox 2 (OTX2) or can be acquired during life." (PMID 37614709, 2023). "Furthermore, in contrast to the phenotype seen in most patients with OTX2 mutations, this family presents a rare example of OTX2 haploinsufficiency manifesting as a hypopituitarism phenotype in the absence of accompanying eye defects (patient 9)." (PMID 33950863, 2021). "OTX2 mutations are rarely associated with hypopituitarism in isolation without eye abnormalities, and may be variably penetrant, even within the same pedigree." (PMID 33950863, 2021).
hypopituitarism (continued). "In humans, mutations in OTX2 have been described in patients with eye defects and variable congenital hypopituitarism (CH), ranging from isolated growth hormone deficiency (IGHD) to combined pituitary hormone deficiency (CPHD) with/without an ectopic posterior pituitary (EPP)." (PMID 33950863, 2021).
depression (9 papers, 2019 to 2025). "OTX2 polymorphisms are associated with bipolar disorders, altered OTX2 methylation is predictive of stress-related depression in children, and the ChP has been linked with major depressive disorders." (PMID 33963285, 2021). "Based on these findings, the researchers proposed that a “two-hit” stress model may be in effect, wherein ELA increases stress susceptibility in the VTA via Otx2 mediation, contributing to a depression-like state and sustained transcriptional alterations in adults following adult social defeat." (PMID 30984237, 2019). "Samples of DNA from children who had suffered maltreatment showed a correlation between the presence of depression and the state of OTX2 gene methylation, and of genes downregulated by OTX2." (PMID 36590919, 2022). "Roles for Otx2 in juvenile and adult control of complex traits such as depression or anxiety have been recently revealed in maltreated children and in mouse models of early-life stress." (PMID 33963285, 2021). "In this study, methylation of the Orthodenticle homeobox 2 (OTX2) gene significantly predicted depression in saliva samples of maltreated children compared to controls." (PMID 30984237, 2019). "Transiently reducing Otx2 in VTA in a late postnatal sensitive period for stress exposure mimicked the effects of ELS on sensitivity to future stress experience and depression-like behavior, while restoring Otx2 levels in this sensitive period rescued the effects of ELS." (PMID 34744836, 2021). "Together, these results suggest the loss of one Otx2 allele does not affect motor activities, cognition, depression-like behavior or sensorimotor gating." (PMID 33963285, 2021).